IL1R1 (interleukin 1 receptor type 1)
Diseases named in the same sentence as IL1R1 in open-access papers (continued):
Sharing a sentence is not in itself a finding about the gene and the disease.
brain injury (2 papers, 2006 to 2019). Acute and chronic (see also brain INJURIES, CHRONIC) injuries to the brain, including the cerebral hemispheres, CEREBELLUM, and brain STEM. "We also reveal that IL-1R1 on cholinergic neurons themselves represent a potential therapeutic target against the detrimental effects of IL-1 after acute brain injury." (PMID 30453020, 2019). "Cumulatively, our studies on gliosis in the IL-1R1-null mice indicate that abrogating IL-1R1 signaling delays some responses of astroglial activation; however, many of the important neuroprotective adaptations of astrocytes to brain trauma are preserved." (PMID 16808851, 2006). "Although IL-1 is known to regulate acetylcholinesterase production and activity of cholinergic neurons, our data implicate for the first time that functional IL-1R1 in cholinergic neurons directly contribute to brain injury and brain oedema in an experimental model of brain injury." (PMID 30453020, 2019).
brain tumors (2 papers, 2006 to 2018). "Further analysis into the functional significance of IL1R1 in EPNs revealed selective upregulation in EPNs as compared to other common brain tumors, strong expression in subventricular zones of juvenile but not adult mice brain, and association with expression of neural stem cell markers." (PMID 30464804, 2018).
chorioamnionitis (2 papers, 2005 to 2018). A morphologic finding indicating inflammation of the fetal sac membranes. "In the pregnancy space, IL-1R1 has been investigated in endometrial tissues and chorioamnionitis and has been found to be increased in PTBs stimulated by RU486 in rats." (PMID 29867970, 2018).
coccidioidomycosis (2 papers, 2015 to 2022). A fungal infection caused by Coccidioides immitis. "By contrast, IL-1R1-deficient mice were reported to have increased disseminated fungal burden, suggesting signalling via IL-1R1 and Myd88 may play a role in coccidioidomycosis immunity in mice." (PMID 35259948, 2022).
colorectal tumor (2 papers, 2021 to 2023). "Regarding the expression of the IL1β receptors, IL1R1 and IL1R2, IL1R1 was strongly expressed in fibroblasts while colorectal tumor cell lines expressed extremely low levels of the receptor." (PMID 34066976, 2021).
cyst (2 papers, 2020 to 2024). A sac-like closed membranous structure that may be empty or contain fluid or amorphous material. "Six weeks post-infection (p.i.)IL-1R1 KO mice displayed an increase in parasite cyst burden in the brain." (PMID 32703941, 2020).
encephalitis (2 papers, 2012 to 2016). An acute inflammatory process affecting the brain parenchyma. "Studies with IL1R1 knockout mice have demonstrated that IL1 is critical for limiting WNV-induced encephalitis in the murine model, purportedly via a T cell activation mechanism and mice inoculated intraperitoneally with WNVNY99 had upregulation of IL6 and IL12 transcripts." (PMID 27267361, 2016).
fibrosarcoma (2 papers, 2022 to 2024). A malignant mesenchymal fibroblastic neoplasm affecting the soft tissue and bone. "(J) mRNA expression of IL1R1 and other key cytokines using xenograft tumours made from either short (HT1080) or long telomere (HT1080-LT) fibrosarcoma cells, and ex vivo HT1080 or HT1080-LT cells." (PMID 39728924, 2024).
gastritis (2 papers, 2016 to 2017). Inflammation of the stomach. "Co-expression of HNF4α and IL-1R1 was a crucial indicator of malignant transformation from gastritis to GC, and was associated with a poorer prognosis in GC patients." (PMID 26870992, 2016). "Examination of clinical samples revealed that HNF4α and IL-1R1 levels increase with increasing severity of Hp-induced gastritis and reach their highest levels in GC." (PMID 26870992, 2016). "Overall, these data reveal that co-expression of HNF4α and IL-1R1 serves as a biomarker in transformation from gastritis to GC and their co-expression indicates worse prognosis of GC." (PMID 26870992, 2016).
helminth infection (2 papers, 2014). "We demonstrate that granuloma formation is inhibited by a pathway involving IL-1R1, type 1 IFNR signaling, and MyD88, but distinct MyD88-dependent mechanisms maintain susceptibility to helminth infection in wild-type mice." (PMID 25114104, 2014).
Intervertebral Disc Degeneration (2 papers, 2024 to 2025). "This study comprehensively analyzed the pathogenesis of Intervertebral Disc Degeneration (IDD) and identified potential target genes, IL1R1 and TCF7L2, closely related to the progression of IDD." (PMID 39050860, 2024). "Using real-time quantitative polymerase chain reaction (qRT-PCR) analysis, we validated the expression levels of two core genes, IL1R1 and TCF7L2, in the Intervertebral Disc Degeneration (IDD) group compared to the normal intervertebral disc group." (PMID 39050860, 2024).
ischemia (2 papers, 2019 to 2020). A hypoperfusion of the BLOOD through an organ or tissue caused by a PATHOLOGIC CONSTRICTION or obstruction of its BLOOD VESSELS, or an absence of BLOOD CIRCULATION. "Supporting the role of IL1 β in ischemia, administration of type 1 interleukin receptor (IL1R1) antagonist or blocking antibodies ameliorates damage induced by excitotoxicity and/or ischemia." (PMID 33302543, 2020).
keratitis (2 papers, 2015 to 2016). A corneal disease that is characterized by inflammation of the cornea. "Analogously, in the A. fumigatus keratitis model both Myd88- and Il1r1-deficient mice demonstrated reduced cellular infiltrate early after inoculation." (PMID 25629406, 2015).
lung adenocarcinoma (2 papers, 2021 to 2023). A carcinoma that arises from the lung and is characterized by the presence of malignant glandular epithelial cells. "In addition, the mRNA expression of IL-1 receptors, IL-1R1 and IL-1RAcp (Minna lab dataset, dbGaP Study Accession is phs001823.v1.p1), and response to IL-1β stimulation, which was measured as fold change in CXCL8 induction, were detected in immortalized normal cells and lung adenocarcinoma cells." (PMID 37985999, 2023).
malaria (2 papers, 2009 to 2018). Malaria is a serious and sometimes fatal disease caused by a parasite that commonly infects a certain type of mosquito which feeds on humans. "We found that the concentrations of malaria specific IgG immunoglobulin in serum were significantly higher in Il1r1−/− mice than in WT mice." (PMID 30470758, 2018). "The higher amount of MyD88-IRF7 dependent type I IFN cytokines in pDCs of Il1r1−/−, Aim2−/−, Nlrp3−/−, and Casp1−/− mice at the early stage of YM infection facilitates anti-malaria adaptive immune response." (PMID 30470758, 2018).
memory (2 papers, 2012 to 2017). The activities involved in the mental information processing system that receives (registers), modifies, stores, and retrieves informational stimuli. "IL1-B, a key cytokine released from glial cells, is critically involved in the pathogenesis of chronic pain, memory deficit, via activation of IL-1R1." (PMID 29069743, 2017).
metabolic syndrome (2 papers, 2022). A cluster of metabolic risk factors for CARDIOVASCULAR DISEASES and TYPE 2 DIABETES MELLITUS. "In conclusion, our study provides important new tools and insights for investigating the role of Il-1β and Il1r1 in a broad spectrum of diseases, such as autoinflammatory diseases, metabolic syndromes, acute and chronic inflammation, and malignancies." (PMID 36389773, 2022).
Neonatal sepsis (2 papers, 2017 to 2020). Systemic inflammatory response to infection in newborn babies. "The deleterious effects of IL-18 on neonatal sepsis survival were dependent upon IL-1R1 signaling and IL-17A production by gamma delta cells in the intestine and lung." (PMID 28224121, 2017). "The study identified that IL-1α, and not IL-1β, was responsible for IL-1R1-dependent lethality during neonatal sepsis." (PMID 32479514, 2020).
osteosarcoma (2 papers, 2022 to 2025). A usually aggressive malignant bone-forming mesenchymal neoplasm, predominantly affecting adolescents and young adults. "For example, IL1B was highly expressed in MDSC, and its receptor IL1R1 was highly expressed in osteosarcoma cells." (PMID 40647416, 2025). "We found that IL1B was highly expressed in MDSC, and its receptor IL1R1 was highly expressed in osteosarcoma cells, along with downstream upregulation of target pathways." (PMID 40647416, 2025).
pituitary tumor (2 papers, 2013 to 2014). A benign or malignant neoplasm affecting the pituitary gland. "The in vitro study performed on the mouse AtT-20 pituitary tumor cells showed that direct LPS treatment increases the number of IL-1R1 in a dose-dependent manner." (PMID 24719525, 2014). "The in vitro study on the mouse AtT-20 pituitary tumor cells showed that direct LPS treatment increases the number of IL-1R1 in a dose-dependent manner." (PMID 23956762, 2013).
retinal degeneration (2 papers, 2020 to 2025). Degeneration of the retina. "Although IL-1β/IL-1R1 signaling has been implicated in cytotoxic processes during retinal degeneration, accumulating evidence points to its pro-survival role under certain conditions." (PMID 40002456, 2025).
rheumatic heart disease (2 papers, 2018 to 2022). An autoinflammatory condition following an infection with Group A Beta Hemolytic Streptococcus (GABHS), in which the heart is attacked by antibodies formed in reaction to a recent GABHS infection. "The comparison between congenital heart disease and rheumatic heart disease in terms of the IL-1β and IL1R1 expression levels revealed a difference between these two types of valvular heart diseases." (PMID 29548280, 2018).
systemic sclerosis (2 papers, 2020). A chronic disorder, possibly autoimmune, marked by excessive production of collagen which results in hardening and thickening of body tissues. "In an Iranian study, the authors reported that some haplotypes of SNPs IL-1A rs1800587, IL-1B rs1143634 and IL1R1 rs2234650 were associated with systemic sclerosis." (PMID 32252823, 2020).
temporal lobe epilepsy (2 papers, 2018 to 2021). A localization-related (focal) form of epilepsy characterized by recurrent seizures that arise from foci within the temporal lobe, most commonly from its mesial aspect. "Increased levels of IL-1β and its receptor (IL-1R1) were found in samples from patients with temporal lobe epilepsy, and this increase was correlated with the frequency of seizures." (PMID 29921762, 2018).
ulcerative colitis (2 papers, 2023 to 2024). An inflammatory bowel disease involving the mucosal surface of the large intestine and rectum. "These Nrg1+Il1r1+ fibroblasts exhibit differentiation potential and actively contribute to epithelial repair during the early stages of ulcerative colitis recovery." (PMID 38674054, 2024).
acute esophagitis (1 paper, 2022). "The interleukin 1 (IL1) family pathway with its downstream effectors (IL1A, IL1R1, IL1RN, IL1B) are esophagus-specific genes and were shown in previous studies to be linked, among others, with the development and progression of acute esophagitis and BE." (PMID 35328735, 2022).
acute liver failure (1 paper, 2020). Rapid deterioration of liver function causing encephalopathy and coagulopathy. "In contrast, IL-1R1 on hepatocytes reduces liver injury in a model of acute liver failure, while deletion of IL-1R1 in pancreatic cells alters glucose homeostasis and triggers β-cell de-differentiation." (PMID 32468079, 2020).
acute lung injury (1 paper, 2025). A condition of lung damage that is characterized by bilateral pulmonary infiltrates (pulmonary edema) rich in neutrophils, and in the absence of clinical heart failure. "IL-1R1 signaling is required for neutrophil extracellular traps (NETs) formation in lipopolysaccharide (LPS)+high-volume ventilation (HVV)-induced acute lung injury (ALI)." (PMID 40553503, 2025).
acute pancreatitis (1 paper, 2024). An acute inflammatory process that leads to necrosis of the pancreatic parenchyma. "Further screening identified four genes (ACSL4, GALNT3, WSB1, and IL1R1) that were significantly upregulated in severe acute pancreatitis (SAP) in both human and mouse samples." (PMID 38862656, 2024).
alcohol liver disease (1 paper, 2015). "Additionally, polymorphisms in the genes encoding the IL-1R antagonist (IL-1ra; Il1rn) and IL-1β (Il1b), but not IL-1α (Il1a) and IL1-R1 (IL-1R1 type 1; Il1r), have been associated with a susceptibility to alcoholism or ALD (alcohol liver disease) in Spanish men." (PMID 25852553, 2015).
Bell's palsy (1 paper, 2024). Partial or complete paralysis of the facial muscles of one side of a person's face. "Previous transcriptomic studies have detected increased interleukin-1 receptor type 1 (IL-1R1) in patients with Bell’s palsy, suggesting that IL-1R1 plays an important role in the occurrence and development of IFP." (PMID 39211643, 2024).
biliary atresia (1 paper, 2020). A rare, biliary tract disease characterized by progressive obliterative cholangiopathy of the intra- and extrahepatic bile ducts, occurring in the embryonic/ perinatal period, leading to severe and persistent neonatal jaundice and acholic stool. "In biliary atresia, a neonatal obstructive cholangiopathy, increased expression of NLRP3, Caspase-1 and IL-1R1 has been demonstrated in the livers of patients at the time of diagnosis." (PMID 32192118, 2020).
bronchiolitis (1 paper, 2022). Inflammation of the bronchioles characterized by swelling of the bronchioles and mucus accumulation. "We also observe an inverse correlation of both IL1R1 and PTGS2 with miR-146a-5p gene expression in bronchiolitis NPAs, suggesting that the reduction in this miRNA could be related to a failure of inflammation resolution." (PMID 36078154, 2022).
cardiomyopathy (1 paper, 2025). A disease of the heart muscle or myocardium proper. "Although IL1R1 has been implicated in aging-associated cardiomyopathy, FCGR3A, EphB3 and Serpin F1 have not been shown to have any effects." (PMID 41020515, 2025).
cervical cancer (1 paper, 2025). A primary or metastatic malignant neoplasm involving the cervix. "Furthermore, we demonstrated that the IL1R1 inhibitor, anakinra, synergized with IR to effectively kill cervical cancer cells." (PMID 39903771, 2025).
chronic fatigue syndrome (1 paper, 2018). "Further supporting this notion, the IL1 receptor antagonist, which potently inhibits IL1β/IL1r1 signaling, was recently found to be ineffective at reducing pain in the treatment of women with chronic fatigue syndrome, which has also been linked to insufficient peripheral perfusion." (PMID 29298725, 2018).
chronic recurrent multifocal osteomyelitis (1 paper, 2025). "Recently, the first clinical case of an autoinflammatory syndrome caused by an autosomal dominant mutation in IL1R1 was identified in a pediatric patient with chronic recurrent multifocal osteomyelitis (CRMO)." (PMID 41087719, 2025).
combined immunodeficiency (1 paper, 2021). A broad classification of inherited disorders presenting at birth that affect both the cell-mediated and humoral aspects of the immune response. "In contrast, when innate or adaptive immunity was compromised, as in severe combined immunodeficiency (SCID) or interleukin-1 receptor 1 (IL-1R1)-deficient mice, significant numbers of cytosolic M. tuberculosis bacilli were detected in the lungs of infected mice." (PMID 33952660, 2021). "For M. tuberculosis, both severe combined immunodeficiency (SCID) mice that lack both T and B cells and IL-1R1 knockout mice were compared to determine their ability to limit cytosolic escape in vivo in infected cells." (PMID 33952660, 2021).
complex regional pain syndrome (1 paper, 2023). A chronic pain syndrome characterized by a disproportionate spontaneous or stimulus-induced pain, accompanied by a variably mixed myriad of autonomic and motor disorders including symptoms such as swelling, allodynia, skin blood supply and trophic disturbances. "Inhibiting the IL-1 receptor 1 (IL-1R1) might be a potential therapeutic opportunity in chronic primary pain conditions such as fibromyalgia and complex regional pain syndrome, which are more common in female patients." (PMID 36982563, 2023).
diabetic retinopathy (1 paper, 2024). "Future studies will also have to identify how other cytokines such as TNFα that have been associated with the development of diabetic retinopathy influence the regulation of the caspase-1/IL-β/IL-1R1 feedback signaling." (PMID 39483336, 2024). "We conclude that any intervention in caspase-1/IL-1β/IL-1R1 feedback signaling presents novel therapeutic options for the treatment of diabetic retinopathy." (PMID 39483336, 2024). "Intervention in the caspase-1/IL-1β/IL-1R1 feedback signaling by inhibition of caspase-1 as shown in this study or by the IL-1 receptor as we previously reported prevents Müller cell death in diabetic retinopathy demonstrating the importance of this signaling pathway to Müller cell viability." (PMID 39483336, 2024).
disseminated candidiasis (1 paper, 2015). Systemic candidiasis occurs when Candida yeast enters the bloodstream and may spread (becoming disseminated candidiasis) to other organs, including the central nervous system, kidneys, liver, bones, muscles, joints, spleen, or eyes. "Additionally, impaired control of pulmonary histoplasmosis and disseminated candidiasis was observed in Il1r1-deficient and Il1a/Il1b-doubly deficient mice, respectively." (PMID 25629406, 2015).
E. coli infection (1 paper, 2016). "Vancomycin-sensitive Gram-positive commensals promoted the expansion of IL-1R1+ γδ T cells, which elicited protection against peritoneal E. coli infection via improved neutrophil recruitment." (PMID 27658245, 2016).
ependymoma (1 paper, 2018). A WHO grade II, slow growing tumor of children and young adults, usually located intraventricularly. "This selective expression of IL1R1 in ependymomas suggests the possibility of IL1R1 serving as a diagnostic marker for intracranial ependymomas and a potential therapeutic target." (PMID 30464804, 2018). "Although multivariate analysis could not be performed due to small number of events in our cohort, we confirmed the poor prognosis of high IL1R1 expression in an independent external ependymoma cohort GSE27287 (p=0.027)." (PMID 30464804, 2018).
gastric diseases (1 paper, 2016). "Our data insinuates that, due to the dual receptor response to Hp infection composed by nuclear receptor HNF4α and its target IL-1R1, a combined therapeutic strategy might be more efficient in controlling NF-κB activation for Hp associated gastric diseases." (PMID 26870992, 2016).
glaucoma (1 paper, 2024). Increased pressure in the eyeball due to obstruction of the outflow of aqueous humor. "The three hub genes SERPINA3, IL1R1, and LCN2 were validated as potential diagnostic biomarkers through real-time PCR, showing increased expression in the OGD/R-induced glaucoma model." (PMID 39125762, 2024). "Moreover, three hub genes, SERPINA3, IL1R1, and LCN2, were validated as potential diagnostic biomarkers for high-risk glaucoma patients, showing increased expression in the OGD/R-induced glaucoma model." (PMID 39125762, 2024).
Gliosis (1 paper, 2022). Gliosis is the focal proliferation of glial cells in the central nervous system. "Ribosomal tagging revealed enteric gliosis as an early part of POI pathogenesis, and mice with an EGC-restricted IL1R1-deficiency failed to develop postoperative enteric gliosis, showed diminished immune cell infiltration, and were protected from POI." (PMID 35962064, 2022).
Headache (1 paper, 2023). Cephalgia, or pain sensed in various parts of the head, not confined to the area of distribution of any nerve. "However, whether IL-1R1 is involved in post-concussive symptoms such as headaches is currently unknown." (PMID 37884959, 2023).
Hearing impairment (1 paper, 2021). A decreased magnitude of the sensory perception of sound. "SNP rs2234650 of IL1R1 had not been previously reported to be associated with hearing impairment." (PMID 34865658, 2021).